EPO (erythropoietin)
Diseases named in the same sentence as EPO in open-access papers (continued):
Sharing a sentence is not in itself a finding about the gene and the disease.
kidney disease (continued). "Finally, the potential use of novel drugs such as PHD inhibitors and SGLT2 inhibitors, stabilizing HIF and inducing EPO production also question the dogma of the detrimental effect of this pathway during renal disease." (PMID 38597413, 2024). "In this scenario, renal disease prompts a reduction in EPO to inhibit bone-mediated RBC production." (PMID 39911241, 2024). "On the other hand, renal diseases could decrease erythropoietin levels, which thus reduces hemoglobin production." (PMID 35360720, 2022). "The mechanism underlying the reduced red blood cell number remained unexplored, but a defect in erythropoiesis or erythrocyte maturation could be a contributing factor whereby the kidney disease affects renal erythropoietin production." (PMID 26839400, 2016). "While erythropoietin can disengage macrophagesby stopping the activity of NF-κB, itis possible that one of the mechanisms explainingthe antifibrotic effects of erythropoietin inchronic kidney disease is in vivo macrophageregulation." (PMID 24381864, 2014). "EPO can block apoptotic injury through the maintenance of mitochondrial membrane potential and the inhibition of caspase activity during cardiovascular injury, renal disease, metabolic injury, and neurodegeneration." (PMID 22388478, 2012). "Interestingly, in mice subjected to the kidney disease model of unilateral ureter obstruction, EPO expression could indeed be detected in the papilla." (PMID 40853869, 2025). "Also recent studies revealed that erythropoietin has protective effect on kidney diseases." (PMID 34059008, 2021). "However, in renal disease conditions the extra-renal tissues, such as the liver, might assume a higher part on the compensatory synthesis of EPO." (PMID 26712750, 2015). "Calcitriol may also support erythropoiesis by directly stimulating erythroid progenitors alongside erythropoietin (EPO), reducing the need for higher EPO doses, as seen in kidney disease and pregnancy." (PMID 39727427, 2024). "Individuals with kidney disease retain the ability to generate EPO, and desidustat, categorized as an oral HIF-PHI, triggers the production of endogenous EPO, maintaining levels within or close to the physiological range and resulting in an elevation of Hb levels." (PMID 38989377, 2024). "Erythropoietin, vitamin D3 and VEGF promote the formation of Tregs, suggesting that receptors for these molecules on T cells might be therapeutic targets in kidney disease and might also contribute to a possible PD-1 immunotherapeutic response." (PMID 33676416, 2021). "Mice with CKD in the EPO cohort treated with saline had significantly elevated creatinine and blood urea nitrogen (BUN) compared with control‐diet fed mice treated with saline, indicating renal disease induction." (PMID 32476270, 2020). "Importantly, our preliminary RT-PCR experiments detected the expression of mRNAs for EPO, HIF2α, and CD73 in cultured cells from the urine of patients with kidney disease, indicating that the exfoliated cell cultures contain REP cells and/or MF-REP cells." (PMID 31798631, 2019). "This indicates that the ability of the kidneys to produce erythropoietin (EPO) and regulate the acid hydrolysis balance is reduced, and renal function is impaired in the early stages of non-simple renal disease in children." (PMID 37576146, 2023).
cardiovascular disease (41 papers, 2009 to 2024). "The erythropoietin demand is a critical risk factor for cardiovascular disease; thus, it is urgent to identify the main causes for erythropoietin demand and epidemiology of increased EPO demand in maintenance dialysis patients with ESRD and its risk predictors/factors." (PMID 32318578, 2020). "However, since these therapeutics induce major side-effects, including elevated risk of cardiovascular diseases, the reinforcement of endogenous EPO production has been suggested as an alternative approach for the treatment of CKD-associated anemia." (PMID 31332228, 2019). "We speculated that increased EPO might be associated with increased risk of subsequent cardiovascular diseases in SA patients." (PMID 28280920, 2017). "These predictors included PD duration, cardiovascular disease, statins, EPO, TC, sTf, roxadustat initial dosage, TCO2, PLR, NLR, age, hemophosphates, ALP, and BNP." (PMID 38561363, 2024). "From a clinical point of view, HDx can be successfully prescribed in the contest of cardiovascular diseases, secondary immunodeficiency, and erythropoietin resistance." (PMID 32408613, 2020). "Beyond erythropoiesis, EPO has been shown to exert beneficial effects in neurodegenerative disorders, cardiovascular diseases and in the immune system." (PMID 32471308, 2020). "The subgroup analysis of the present study indicated that SA patients with cardiovascular disease had significantly higher EPO levels." (PMID 28280920, 2017). "Emerging evidence indicates the crucial influence of EPO on the regulation of physiological functions of cardiovascular system and the pathogenesis of cardiovascular diseases." (PMID 26101463, 2015). "Recent studies reported that EPO increases the number and function of bone marrow derived endothelial progenitor cells in cardiovascular diseases." (PMID 25119659, 2014). "Little information on EPO's effect in obese subjects is available due to concern about EPO's role in promoting cardiovascular disease by increasing the haematocrit level and blood pressure in these patients." (PMID 19521513, 2009). "The reasons for the decreased exercise in DKD patients may include difficulty in controlling blood sugar, decreased muscle function, co-morbidities such as cardiovascular disease, and reduced hemoglobin levels due to decreased erythropoietin production." (PMID 39526249, 2024). "Cardiovascular diseases can cause erythrocytosis through chronic hypoxia, but no obvious increase in EPO levels was observed in patients with NNE." (PMID 35775283, 2023). "Generation of EPO-producing MSCs by genetic engineering has been reported to enhance the benefits of MSC-based treatments in cardiovascular disease by improving their promotion of the angiogenic response and survival potential via endocrine and autocrine mechanisms, respectively." (PMID 32993806, 2020). "EPO has also been identified to play an important role in the mechanism of cardiovascular diseases." (PMID 28280920, 2017). "We speculated that elevated EPO levels in patients with SA and cardiovascular disease were an adaptive response against intermittent hypoxia." (PMID 28280920, 2017). "We could exclude increased odds of 1.15 for cardiovascular disease for a 2.2-unit EPO increase." (PMID 36055212, 2022). "Outcomes included measures of mortality, cardiovascular disease, inflammation, muscle strength/function, nutrition, patient well-being, and outcomes specific to ESKD including erythropoietin usage, pruritus, and dialysis access maturation." (PMID 37447398, 2023). "The hormone erythropoietin, secreted during hypoxia, promotes the release of enlarged RBCs, leading to an abnormal increase in RDW in cardiovascular diseases." (PMID 36494633, 2022).
neurodegenerative disease (32 papers, 2009 to 2026). A disorder of the central nervous system characterized by gradual and progressive loss of neural tissue and neurologic function. "Erythropoietin (EPO), a glycoprotein hormone traditionally associated with erythropoiesis, has shown promise as a neuroprotective agent in preclinical models of neurodegenerative diseases." (PMID 40585228, 2025). "EPO has also been described as a positive effector for neurodegenerative diseases in the human system." (PMID 36879191, 2023). "Numerous studies explored the therapeutic effects of erythropoietin (EPO) on neurodegenerative diseases." (PMID 35250554, 2022). "Under the gene delivery approaches, EPO has significant therapeutic potential in neurodegenerative diseases due to its neuroprotective effects." (PMID 35806148, 2022). "As erythropoietin (EPO) is emerging for its benefits in neurodegenerative diseases, here, we test the protective effect driven by EPO in in vitro (SH-SY5Y cells challenged by MPP+) and in vivo (C57BL/6J mice administered with MPTP) PD models." (PMID 33467745, 2021). "Several animal models have shown a neuroprotective action of EPO in neurodegenerative diseases when injected intravenously or infused directly into the brain." (PMID 33909634, 2021). "Erythropoietin (EPO), primitively known for their hematopoietic effects, has been evidenced to possess neuroprotective function in neurodegenerative diseases recently." (PMID 28299330, 2017). "In this perspective, administration of erythropoietin (EPO) has recently raised interest in the treatment of neurodegenerative diseases, including CM." (PMID 27441662, 2016). "Among new treatment strategies, EPO therapy to retard the course of neurodegenerative diseases and slow down their damaging effects is considered promising." (PMID 24761770, 2014). "Erythropoietin has been proven as a hypoxia-responsive cytokine to provide protective effects in the damaged brain during hypoxic/ischemic events and neurodegenerative diseases." (PMID 23596515, 2013). "In summary, we conclude that the presented data support further research for the treatment of neurodegenerative diseases as EPO is acting anti-apoptotic in human NPCs." (PMID 21126346, 2010). "Conversely, hS3 mRNA expression is reduced below EPO levels in neurodegenerative disease." (PMID 41602576, 2026). "These biomarkers include glycated hemoglobin (HbA1c), C-reactive protein (CRP), erythropoietin (EPO), interleukin-6, uric acid, endocan, copeptin, and numerous other molecules involved in the pathogenesis of neurodegenerative diseases, lipid, and vascular metabolic pathways." (PMID 37371460, 2023). "In animal models of neurodegenerative diseases including AD, neuroprotective and neuroregenerative mechanisms of EPO are related to inhibiting apoptosis, reducing oxidative stress and inflammation, promoting the angiogenesis and neurogenesis, and maintaining blood brain barrier (BBB) integrity." (PMID 29745864, 2018). "Our findings also provide supporting evidence for the notion that the neural protective function of EPO could be applied for treating PD and other neurodegenerative diseases." (PMID 27872856, 2016). "Understanding the mechanism by which EPO modulates neuroinflammation may lead to novel therapeutic strategies for the treatment of neurodegenerative diseases and injuries." (PMID 25374571, 2014). "In summary, EPO in combination with G-CSF might be a feasible therapeutic strategy to treat different neurodegenerative diseases." (PMID 20404921, 2010). "Our present findings therefore show for the first time an EPO-driven sexual dimorphism in neuronal differentiation of human neural-crest derived stem cells and emphasize sex-specific variability as a crucial parameter in stem cell biology and for treating neurodegenerative diseases." (PMID 36879191, 2023).
neurodegenerative disease (continued). "In addition, the availability of EPO derivatives could potentially lower the costs of EPO treatment and provide new series of treatment options to counteract different neurodegenerative diseases." (PMID 35806148, 2022). "Moreover, we describe for the first time how the protective effect of EPO against neurodegenerative diseases such as PD, may be ascribable to the EPO capability of restoring mitochondria metabolism and morphology." (PMID 33467745, 2021). "In the past few decades, researchers have redirected their attention towards erythropoietin (EPO), an endogenous molecule with a pleiotropic role, although not fully understood, in neurodegenerative diseases." (PMID 33255969, 2020). "In this review, we discuss the neuroprotective effects of several common endocrine hormones, including estrogen, testosterone, erythropoietin (EPO), basic fibroblast growth factor (bFGF), and thyroid hormones (THs), on SCI and some degenerative disease of the central nervous system (CNS)." (PMID 33390881, 2020). "In our study, we established a cellular material for future in vivo studies of neurodegenerative diseases based on EPO provided regionally at a nontoxic level." (PMID 26357589, 2015). "The established EPO-overexpressing NIH/3T3 cell line, EPO-3T3-EGFP, may provide a material for future studies of cell-based therapies for neurodegenerative diseases via the secretion of EPO on a short-term, high-dose, regional basis." (PMID 26357589, 2015). "However, not all degenerative diseases seem to respond to EPO therapy." (PMID 20142991, 2009). "However, researchers have not yet clearly determined how EPO ameliorates the pathological process in the microenvironment of the CNS, and a clear understanding of the protective effects of EPO on SCI and other neurodegenerative diseases is urgently needed." (PMID 33390881, 2020).
neurological diseases (30 papers, 2008 to 2026). "Finally, we believe that pleiotropic function of rhEPO and its molecular variants in the CNS, not only for neurological diseases, can be explained through functional receptor-mediated differential cellular response and not only by the kind of EPO molecule." (PMID 33255969, 2020). "Yet, EPO and each of these downstream pathways require precise biological modulation to avert complications associated with the vascular system, tumorigenesis, and progression of nervous system disorders." (PMID 23109841, 2012). "Although EPO has been approved for the treatment of renal anemia and has been successfully tested in multiple preclinical and clinical trials addressing different neurological diseases, the underlying mechanisms of EPO-conveyed cytoprotection remain poorly understood." (PMID 34628598, 2022). "Recombinant human erythropoietin (Epo) protects against neurodegenerative processes in neurological disorders." (PMID 41242999, 2025). "HIF-1α also upregulates a plethora of genes including vascular endothelial growth factor (VEGF) and erythropoietin, both showing neuroprotective activity in different animal models of neurological diseases." (PMID 34339019, 2021). "In humans, under damage conditions in different neurological disorders, the EPO/EPOR system is upregulated in the brain tissue, and only in some cases in cerebrospinal fluid (CSF), as compared to healthy cases." (PMID 33255969, 2020). "Previous studies have indicated that erythropoietin (EPO) has neuroprotective effects in different neurological diseases." (PMID 32341967, 2019). "Administration of erythropoietin (EPO) is neuroprotective against a variety of experimentally-induced neurological disorders." (PMID 30597853, 2018). "High doses of EPO were used to be injected systemically in neurological disorders to ensure crossing blood brain barrier." (PMID 30647957, 2018). "Exogenous administration of human recombinant EPO is neuroprotective against a variety of experimentally induced neurological disorders." (PMID 30597853, 2018). "Several studies have shown that erythropoietin (EPO) has neuroprotective or neuroreparative actions on diseases of the nervous system and that improves oligodendrocyte (OL) differentiation and myelination in vivo and in vitro." (PMID 29123527, 2017). "EPO exerts remarkable neuroprotection for both, in vitro and in vivo models of nervous system disorders." (PMID 25324845, 2014). "The pleiotropic activity of EPO evident in culture and animal studies remain of continuing interest, particularly its potential treatment for neurological disease." (PMID 22567318, 2012). "Erythropoietin (EPO) is a pleiotropic cytokine with important functions in neuronal development and neuroprotection, but hematopoietic effects limit the therapeutic application of EPO in neurological diseases." (PMID 41602576, 2026). "In addition, to eliminate the deleterious effects, a group of EPO derivatives were developed and showed neuroprotection in animal models of neurological disorders." (PMID 35250554, 2022). "Interventions, including corticosteroids, melatonin, erythropoietin, anti-TNF-α antibodies, and IL-1rα administration, in clinical use for other diseases, may be also utilized for the control of neurological disorders in susceptible neonates." (PMID 32047730, 2020). "Delivery of therapeutic agents as erythropoietin (EPO) into Central Nervous System through intranasal route could benefit patients with neurological disorders." (PMID 28676085, 2017). "The aims of our study were to establish an EPO-overexpressing NIH/3T3 fibroblast cell line and to identify possible neuroprotective effects of secreted EPO to provide a potential material for studies of cell-based therapy in animal models of neurological disorders." (PMID 26357589, 2015). "Several studies indicated that Erythropoietin (Epo) may provide remarkable neuroprotection in some neurological diseases." (PMID 23211059, 2012).
neurological diseases (continued). "Erythropoietin (EPO), a neurotrophic factor that supports the growth, survival, and differentiation of neurons, is a protein whose development as a potential therapeutic material for treatment of neurological disorders is restricted by its inability to traverse the BBB." (PMID 31242683, 2019). "Therefore, this EPO-overexpressing NIH/3T3 fibroblast cell line may represent a potential material for future studies of cell-based therapies for neurological diseases via the secretion of EPO on a short-term, high-dose, and regional basis." (PMID 26357589, 2015). "EPO is a viable candidate because of extensive clinical experience with its use in the treatment of hematologic/anemic disorders and substantial preclinical and emerging clinical experience with its use for the treatment of neurological disease models/disorders." (PMID 22046448, 2011). "Moreover, the rapid clearance of rhNEPO from plasma represents an advantage in the treatment of neurological diseases, because the continuous presence of EPO in blood is the stimulus that triggers the production of sanguineous cells with the resulting appearance of adverse side-effects." (PMID 22373358, 2011). "Especially in neurological disorders, a previous study indicated ARA290 (30 μg/kg, bid) exhibited neuroprotective activities comparable to those of EPO in mild traumatic brain injury (mTBI) followed by hemorrhagic shock." (PMID 38488446, 2024). "Erythropoietin (EPO) is a neuroprotective cytokine, which has been applied in several animal models presenting neurological disorders." (PMID 25324845, 2014). "In our study, we addressed a new biological material for neurological diseases based on EPO provided regionally at a nontoxic level; for instance, cell-based therapy." (PMID 26357589, 2015). "A mouse EPO cDNA was subcloned into the pCMS-EGFP vector and transfected into NIH/3T3 fibroblasts to design a biological provider that can regionally release EPO for the treatment of neurological diseases." (PMID 26357589, 2015). "Yet, it is important to note that the expression of EPO and the EPOR may lead to variable biological outcomes that can be beneficial for nervous system disorders, but also may promote detrimental outcomes such as aggressive tumor growth and decreased overall survival." (PMID 23109841, 2012). "Alternatively, although not specific an enhancer of EPO sensitivity, targeting the protective tissue-specific effects of EPO might prove a viable therapeutic target, although to date, this was mostly evaluated in neurological disorders." (PMID 31551803, 2019).